GBX2 (gastrulation brain homeobox 2)
Description:
May act as a transcription factor for cell pluripotency and differentiation in the embryo.
Tractability: No criterion of Open Targets' tractability assessment is met for any kind of drug.
Gene: Protein-coding gene on chromosome 2 (236,165,236 to 236,168,386, reverse strand). Ensembl gene ENSG00000168505.
Subcellular location: Nucleus
Subcellular location (Human Protein Atlas): Nucleoplasm
Pathways (Reactome):
Developmental Biology: Formation of the anterior neural plate; Formation of the posterior neural plate; Specification of the neural plate border
Gene Ontology:
Molecular function: sequence-specific double-stranded DNA binding; DNA-binding transcription factor activity; DNA-binding transcription factor activity, RNA polymerase II-specific; RNA polymerase II transcription regulatory region sequence-specific DNA binding; DNA binding; DNA-binding transcription activator activity, RNA polymerase II-specific; RNA polymerase II core promoter sequence-specific DNA binding; RNA polymerase II-specific DNA-binding transcription factor binding
Biological process: nervous system development; regulation of nervous system development; regulation of transcription by RNA polymerase II; positive regulation of transcription by RNA polymerase II; regulation of DNA-templated transcription
Cellular component: chromatin; nucleus
Genetic constraint (gnomAD): Loss-of-function variants: 5 observed, 17.65 expected, observed/expected ratio (o/e) 0.28, 90% interval 0.15 to 0.6. The upper end of that interval is the gene's LOEUF score, 0.6, which puts it in group 2 of 6, group 1 being the genes least tolerant of losing a copy. Missense variants: 470 observed, 434.51 expected, observed/expected ratio (o/e) 1.08, 90% interval 1 to 1.17. Synonymous variants: 220 observed, 196.78 expected, observed/expected ratio (o/e) 1.12, 90% interval 1 to 1.25.
Homologues: Orthologues: chimpanzee GBX2 (99% identical), macaque GBX2 (99% identical), dog GBX2 (99% identical), pig GBX2 (99% identical), mouse Gbx2 (98% identical), rat Gbx2 (98% identical), rabbit GBX2 (96% identical), guinea pig GBX2 (94% identical), tropical clawed frog gbx2 (80% identical), tropical clawed frog gbx2.2 (78% identical), zebrafish gbx2 (73% identical), Drosophila melanogaster unpg (41% identical). Paralogues in human: GBX1 (51% identical).
Diseases named in the same sentence as GBX2 in open-access papers:
GBX2 is named in the same sentence as 24 diseases in open-access papers, as found by Europe PMC text mining. Sharing a sentence is not in itself a finding about the gene and the disease. The quoted sentences say what the papers report.
prostate carcinoma (5 papers, 2012 to 2021). A carcinoma that arises from epithelial cells of the prostate gland. "These include TBX3, which promotes epithelial to mesenchymal transition and predicts poor prognosis in colorectal cancer, and GBX2, which promotes growth of breast and prostate cancer cells." (PMID 34611476, 2021). "We have previously demonstrated that GBX2 directly targets NRP1 in human prostate cancer cells (PC-3)." (PMID 33322598, 2020). "GBX2 is overexpressed in prostate cancer and studies show that expression of GBX2 is required for malignant growth of human prostate cancer." (PMID 31277598, 2019). "To identify candidate target genes directly regulated by GBX2, we preformed chromatin immunoprecipitation assays coupled with high-throughput sequencing (ChIP-Seq), using PC-3 cells, a human prostate cancer line." (PMID 23144817, 2012). "Using chromatin immunoprecipitation coupled with direct sequencing (ChIP-Seq) analysis in a human prostate cancer cell line, we identified cis-regulatory elements bound by GBX2 to provide insight into its direct downstream targets." (PMID 23144817, 2012). "Gastrulation brain homeobox 2 (GBX2) downregulation also suppresses proliferation, invasion, and angiogenesis of breast cancer cells through inhibiting Wnt/β-catenin signaling and reduces growth of prostate cancer xenografts." (PMID 33632299, 2021).
breast carcinoma (4 papers, 2011 to 2021). "GBX2 (gastrulation brain homeobox 2) gene silencing has an inhibition effect on invasion, proliferation and angiogenesis by inhibiting the activation of the Wnt/β-catenin signaling pathway in breast cancer cells." (PMID 33921847, 2021). "In conclusion, in our study, we demonstrate that Musashi protein knockdown downregulates several important stem cell characteristics in breast cancer, including CD44, vimentin and GBX2, likely due to Notch pathway downregulation." (PMID 32245259, 2020).
DiGeorge syndrome (3 papers, 2012 to 2021). "Importantly, loss of Gbx2 function modulates the Slit/Robo signaling pathway, resulting in abnormal NC cell migration and abnormalities resembling congenital diseases such as DiGeorge syndrome, in which the main cause of death is congenital heart defects." (PMID 23144817, 2012). "Identification of these direct target genes should advance our understanding of the functions of GBX2 and provide greater insight into the relationships of GBX2 and various congenital diseases such as Usher and DiGeorge Syndromes." (PMID 23144817, 2012). "The loss of GBX2 function also modulates the Slit/Robo-signaling pathway, leading to abnormal NCC migration and abnormalities that as similar to those in congenital diseases, such as DiGeorge syndrome and in craniofacial malformations." (PMID 34426786, 2021).
Usher syndrome (2 papers, 2012 to 2019). A syndromic diseae characterized by the association of sensorineural deafness (usually congenital) with retinitis pigmentosa and progressive vision loss. "EF1A1, together with genes associated to the Usher syndrome, a congenital disease characterized by perturbation of normal organization and growth of hair bundles within the inner ear, is a downstream target of GBX2, which induces EF1A1 activation upon binding to the EF1A1 core promoter." (PMID 31708969, 2019). "Similar to many mouse models for Usher syndrome, Gbx2−/− embryos display cochlear and vestibular sensory defects in the inner ear." (PMID 23144817, 2012). "Several of the top candidate genes include EEF1A1, ROBO1, PLXNA4, SLIT3, NRP1, and NOTCH2, as well as genes associated with the Usher syndrome, PCDH15 and USH2A, and are plausible candidates contributing to the developmental defects in Gbx2−/− mice." (PMID 23144817, 2012).
adenoma (1 paper, 2021). A neoplasm arising from the epithelium. "Expression changes detected by RNA-seq were validated in an expanded set of samples by RT-qPCR for IL10, SOX9, GBX2, and HOXA5, genes with biological functions that may contribute to the reduced progression of hyperplasia to adenoma." (PMID 33632299, 2021).
laryngeal squamous cell carcinoma (1 paper, 2021). A squamous cell carcinoma that arises from the larynx. "In laryngeal squamous cell carcinoma, miRNA-4497 significantly promotes apoptosis of cancer cells, most likely through a negative modulation of the GBX2 (gastrulation brain homeobox 2) gene." (PMID 33579314, 2021).
medulloblastoma (1 paper, 2014). A malignant, invasive embryonal neoplasm arising from the cerebellum. "Known developmental repressors of OTX2 in the hindbrain include Gbx2 and Fgf8; however, these genes are rarely expressed in established medulloblastomas." (PMID 25198066, 2014).
osteoarthritis (1 paper, 2021). A noninflammatory degenerative joint disease occurring chiefly in older persons, characterized by degeneration of the articular cartilage, hypertrophy of bone at the margins and changes in the synovial membrane. "Gbx2 and other early responder TFs should be considered in mechanistic models that clarify cartilage-anabolic changes in the clinical progression of osteoarthritis." (PMID 34765608, 2021).
triple-negative breast carcinoma (1 paper, 2018). An invasive breast carcinoma which is negative for expression of estrogen receptor (ER), progesterone receptor (PR), and human epidermal growth factor receptor 2 (HER2). "Gbx2 was shown to be a marker of chemoresistance in triple negative breast cancer." (PMID 29625565, 2018).
cancer (5 papers, 2011 to 2025). A tumor composed of atypical neoplastic, often pleomorphic cells that invade other tissues. "This included genes like, PIK3R2, PIK3CA, BIRC2 and ZBTB14 with implications in cancer that were over-expressed with FC above ≥10 in OS-DW in comparison to OS-R; while, expression of WNT5A, PIK3CB, ACVR1, MAPK13 and GBX2 were significantly reduced." (PMID 31690262, 2019). "Indeed, several of the 15 synergistic DEGs we validated are directly or indirectly associated with acquisition of stem-like phenotypes in normal or cancer cells, particularly SNAI1, SOX9 and GBX2." (PMID 25401416, 2014).
tumor (3 papers, 2018 to 2025). "The tumor tissues displayed an enriched expression of transcription factors (e.g., Dlx2, Gbx2, Foxb1, and Nkx2.2) critical for brain development, tanycyte markers (e.g., Ptprz1, Fabp7, Crym, and Gja1), and differentiation markers (e.g., Dcx, Olig1, and Cspg5)." (PMID 33863883, 2021). "However, how and whether Gbx2 and HDAC involve SALL1-mediated tumor cell DNA damage and senescence is still unknown in the current study." (PMID 29625565, 2018).
neurological disease (1 paper, 2017). "We believe that our current study linking Gbx2 expression, cell lineage, and cell fate in the Cb may provide valuable context for understanding neurological disease." (PMID 28785208, 2017).
GBX2 also shares sentences with these, for which no sentence is quoted: glioma (3 papers); gastric cancer (2); Alzheimer disease (1); attention deficit/hyperactive disorder (1); colorectal cancer (1); depression (1); gout (1); head and neck squamous cell carcinoma (1); hyperplasia (1); microcephaly (1); Parkinson disease (1); type 2 diabetes mellitus (1).